NOD2 (nucleotide binding oligomerization domain containing 2)
Diseases named in the same sentence as NOD2 in open-access papers (continued):
Sharing a sentence is not in itself a finding about the gene and the disease.
colitis (continued). "In accord with prior studies in which NOD2 regulation was assessed, we first determined the ability of over-expressed (intact) WT-NOD2 and/or CD-frameshift-NOD2 versus over-expressed BS-NOD2 to protect mice from the induction of TNBS-colitis." (PMID 36189261, 2022). "These previous studies showed that in vivo cross-regulation and protection from colitis is abrogated in IRF4-deficient mice and NOD2 activation facilitates IRF4-mediated de-ubiquitination of key factors necessary for NF-κB activation." (PMID 36189261, 2022). "Existing studies have demonstrated that Nod2 knockout mice displayed more severe enteritis compared with wild-type mice in the experimental colitis model." (PMID 36506547, 2022). "This is similar to the report that NOD2 signaling contributes to intestinal inflammation and the development of colitis in patients with inflammatory bowel disease in the absence of IL-10 signaling." (PMID 34768828, 2021). "This idea is fully supported by our recent report in which NOD1 or NOD2-independent activation of RIPK2 mediates experimental colitis." (PMID 33935757, 2021). "Human UCSCs were shown to reduce colitis in a DSS-induced mice colitis model by activating NOD2 signaling to COX2." (PMID 33287220, 2020). "Recognition of muropeptide from Lactobacilli by NOD2 can induce anti-inflammatory properties and protect mice from colitis development." (PMID 33195367, 2020). "Structural analysis suggests that PGNs from anti-inflammatory strains contain a muropeptide, M-tri-Lys, that mediates the protective roles of PGNs in colitis in a NOD2-dependent, but MyD88-independent manner." (PMID 32719681, 2020). "PGN purified from Lactobacillus salivarius Ls33, a strain that has protective effects in colitis, induces IL-10-producing DCs in a NOD2-dependent manner in vitro and protects mice from colitis in an IL-10-dependent manner." (PMID 32719681, 2020). "Nod2−/− mice are not more susceptible to dextran sodium sulfate (DSS)-induced colitis than wild-type controls; however, Nod2−/− mice develop signs of colitis in the T cell-induced mucosal damage model." (PMID 31109951, 2019). "Nod2−/− endow potentially useful microbes beneficial for Nod2+/+ when colitis occurs, providing them with more “volatile” microbial families and genera, most likely linked to the relative short time of colonization." (PMID 30250234, 2018). "For example, Bacteroides fragilis can secrete capsular polysaccharide A to induce expression of interleukin-10 from regulatory T cells and protect mucous from colitis in a NOD2- and ATG16L1-dependent way." (PMID 29404425, 2018). "In co-housed mice the acquisition of Rickenellaceae by Nod2+/+ mice was associated with increased CD4+ LAP+ Foxp3− proportion and less severe colitis." (PMID 30250234, 2018). "Deficiency for Card9 gene, an adaptor protein, acting downstream of Nod2 on the MAPK pathway, confers an increased susceptibility to colitis and shows an altered gut microbiota profile and metabolism." (PMID 29868004, 2018). "On the other hand, Nod2+/+ can expose Nod2−/− to microbial species that these cannot normally control, and that can be potentially harmful during colitis." (PMID 30250234, 2018). "Simultaneously, a transmissible risk of colitis and CAC in Nod2-deficient mice transiently co-housed with wt mice in the context of AOM-DSS treatment has been observed in another study." (PMID 29868004, 2018). "It has been known that MDP activation of NOD2 has protective effect against several diseases, such as colitis, atherosclerosis, and influenza infection, in mice." (PMID 29163541, 2017). "In another study by Jamontt and colleagues, however, Nod2 was shown to promote IL-10−/− colitis, given that Nod2−/− IL-10−/− mice were protected from colitis development." (PMID 28592996, 2017). "An increased susceptibility to DSS-induced colitis was also reported for mice deficient for the cytosolic NOD-like receptors (NLRs) NOD1 and NOD2." (PMID 25068517, 2014).
colitis (continued). "These discrepant findings led us to further investigate the intrinsic role of Nod2 in T cell function and in the induction of colitis." (PMID 24324812, 2013). "Members of the Nucleotide oligomerization domain (NOD)-like receptor family such as nucleotide oligomerization domain 2 (NOD2) are involved in the intestinal immune response by regulating the initiation and progression of colitis." (PMID 23882266, 2013). "In conclusion, our data indicate that Nod2 is functional in murine CD4+ T cells but its expression is dispensable for the T cell regulation of colitis." (PMID 24324812, 2013). "Using a new mouse model invalidated for Card15/Nod2 (KO), we thus analysed the impact of the gene in these lymphoid formations together with the development of experimental colitis." (PMID 17565376, 2007). "Because GIV is required for the protective effects of MDP/NOD2 signaling in DSS-induced colitis, we examined whether this protection involves modulation of iColAM and niColAM populations in a GIV-dependent manner." (PMID 40766554, 2025). "On the one hand, MDP activates the NOD2 signaling pathway, thereby promoting the secretion of antibacterial peptides, upregulating the expression of tight junction proteins, repairing the intestinal epithelium, and exerting an anti-colitis effect." (PMID 40703925, 2025). "Moreover, upon the deletion of NOD2 in IL-10/mice, a remarkable improvement in the symptoms of colitis was observed." (PMID 40692778, 2025). "Building on this, recent work has delineated the unique role of NOD2 in Norovirus-induced colitis." (PMID 41020029, 2025). "However, these protective effects of MDP were absent in Otub2–/– mice, indicating that OTUB2 is essential for NOD2‐mediated protective effects in colitis." (PMID 39358938, 2024). "Importantly, attenuation of DSS-induced colitis by NOD2 activation was accompanied by decreased and increased expression of type I IFNs and DUBA, respectively, in the colon." (PMID 39403381, 2024). "Thus, MDP-mediated activation of NOD2 prevents the exacerbation of DSS-induced colitis induced by TLR9 activation." (PMID 39403381, 2024). "LPH administration protects mice from TNBS-induced colitis in an NOD2-dependent manner." (PMID 39403381, 2024). "Since NOD2-mediated gut homeostasis is also critical for protecting against CRC31–33, we next evaluated LPH’s protective effects on azoxymethane (AOM)/DSS induced colitis-associated colon cancer model." (PMID 37286542, 2023). "A recent study suggested that DL-endopeptidase-producing L. salivarius could promote the restoration of the pattern-recognition receptor NOD2 in mice with CD, and further exerted potent anti-colitis effects." (PMID 36814443, 2023). "Furthermore, mice injected with MDP were protected against TNBS- or DSS-induced colitis by the suppression of multiple TLR pathways suggesting a cross-tolerization of TLRs by chronic NOD2 stimulation." (PMID 37415975, 2023). "To analyze if the colitis-protective effects were associated with the ability to generate NOD2 ligands in vivo, we detected NOD2 ligands after administration of LPH or its mutants at different dosages using HEK293 NOD2 reporter cells." (PMID 37286542, 2023). "In 2004, an early study showed that the p38 mitogen-activated protein kinase (MAPK) inhibitor SB203580 could suppress DSS-induced experimental colitis via inhibiting NOD2 effector RIPK2 in the NOD2/RIPK2/NF-κB signaling pathway." (PMID 37833958, 2023). "The differential effect of NOD2 in a model of colitis and ileitis may explain why the involvement of the transverse colon, left colon, or rectum was significantly less common among CD patients bearing NOD2 mutations." (PMID 37876927, 2023). "In addition to these important probiotic proteins, another study found that the probiotic species Lactobacillus salivarius also protects against colitis through the NOD2 pathway." (PMID 37286542, 2023).
colitis (continued). "In TNBS-induced colitis, a genetic association between NOD2 and inflammation has been demonstrated, which is absent in UC." (PMID 37427322, 2023). "Indeed, the construction of mice that overexpress NOD2 demonstrated their resistance to TLR2 ligation as well as a significantly reduced resistance to TNBS-colitis." (PMID 36012618, 2022). "NOD2 activated by MDP could reduce intestinal injury in murine colitis and MDP may inhibit Toll-like receptors (TLR2 or TLR4) mediated pro-inflammatory signal pathway to decrease the expression of nuclear factor kappa-B (NF-κB)." (PMID 36506547, 2022). "Moreover, Nod2−/− mice exhibit more severe colitis and an increased abundance of intestinal Aspergillus, E. coli/Shigella, and Enterococcus spp." (PMID 35954484, 2022). "The enrichment of Alistipes, together with anti-inflammatory cytokine IL-10 and regulatory T cells, could attenuate severe colitis in NOD2 knockout mice." (PMID 35736237, 2022). "These in vivo data, in showing that the presence of the BS-NOD2 transgene leads to more severe TNBS-colitis than observed in WT mice, suggests that BS-NOD2 over-rides or disturbs the protective effect of endogenous NOD2 as a result of a dominant-negative effect." (PMID 36189261, 2022). "Taken together, whereas WT NOD2 HVJ-E-mediated over-expression protected mice from induction of TNBS-colitis, similar BS-associated NOD2 over-expression did not; in this respect BS-NOD2 was similar to CD-frameshift NOD2." (PMID 36189261, 2022). "Previous studies have shown that a deficiency in NOD2 or NLRP6 results in a colitogenic microbiota that can exacerbate DSS-induced colitis, and the aggravated colitis phenotype exhibited by NOD2−/− or NLRP6−/− mice could be transferred to WT mice by cohousing." (PMID 35761415, 2022). "Using Nod2 KO mice that develop spontaneous colitis, it was observed that T. muris infection induces Th2 immunity that leads to the expansion of the beneficial bacteria Clostridiales that competitively inhibits colitogenic Bacteroides vulgatus and ultimately decreases the severity of colitis." (PMID 34451389, 2021). "In addition, Nod2 was reported to mediate an alleviative effect on dextran sulphate sodium (DSS)-induced colitis mice models via suppressing the gram-positive bacteria invasion and damage, while knocking out Nod2 abolished such effects." (PMID 34899362, 2021). "The loss of NOD2 in IL-10-deficient macrophages reduced the production of IL-6, TNF and IL-12p40 in response to bacterial stimulation and thus dampened the usual hyper-responsiveness in the colitis mice." (PMID 34768828, 2021). "Thus, SIgA reverse transcytosis seems to play a role in colitis induction by a NOD2-mediated increased transport of pathogens." (PMID 33431850, 2021). "It was found that the NOD2 knock-out mice had less severe colitis than the wild-type." (PMID 32582143, 2020). "Moreover, Ls33 peptidoglycan stimulated dendritic cell and T-cell regulatory functions upon sensing of nucleotide-binding oligomerization domain protein 2 (NOD2), and rescued mice from colitis induced by trinitrobenzene sulfonic acid (TNBS)." (PMID 33195367, 2020). "Both PGLYRP-3 and NOD2 recognize the bacterial PGN and play a synergistic role in maintaining intestinal microbiota and inflammation as PGLYRP-3−/− NOD2−/− double-knockout mice were more sensitive to DSS-colitis than PGLYRP-3−/− or NOD2−/− single knockout animals." (PMID 31416116, 2019). "In a dextran sulfate sodium-induced colitis model, oral administration of fungal chitin reduced the inflammatory parameters and leukocyte infiltration into the gut mucosa and increased IL-10 production via stimulation of NOD-2 and TLR8." (PMID 31781518, 2019). "Apart from various reports on mice, convincing data directly connecting NLRs and human CRC are available only for NOD1, NOD2 and NLPR3, which were found to be associated with susceptibility, progression and treatment of sporadic CRC, colitis and/or colitis-associated CRC." (PMID 29928061, 2018).
colitis (continued). "Indeed, a Nod2-dependent protective effect of the strain Lactobacillus salivarius Ls33 has been described in a mouse model of 2,4,6-trinitrobenzene induced colitis." (PMID 29868004, 2018). "In contrast, overexpression of the NOD2 gene rescued mice from peptidoglycan-induced colitis, and mice deficient in TLR9 and MyD88 no longer demonstrated probiotic-mediated inhibitory effects on intestinal inflammation in experimental colitis." (PMID 29892282, 2018). "Depending on the applied in vivo model Nod2 might either prevent from or even enhance colitis development in C. jejuni infected mice." (PMID 28592996, 2017). "Whereas, MDP application could prevent from 2,4,6-trinitrobenzenesulphonic acid (TNBS) colitis, preventive properties of MDP were abrogated in Nod2 deficient mice indicative for a protective role of Nod2 signaling." (PMID 28752081, 2017). "Similarly, infection of Nod1−/− and Nod1/Nod2 double-knockout mice revealed that both Nod1 and Nod2 play a protective role in S. Typhimurium ΔmsbB-induced colitis." (PMID 25423082, 2014). "We recently demonstrated that MSCs can suppress mononuclear cell proliferation and reduce the severity of colitis in mice by producing PGE2 via the nucleotide-binding oligomerization domain 2 (NOD2)-receptor-interacting serine/threonine-protein kinase 2 (RIP2) pathway." (PMID 25090227, 2014). "However, NOD2 was also reported to promote the secretion of the anti-inflammatory cytokine IL-10 as well as proliferation of regulatory T cells during murine colitis." (PMID 25068517, 2014). "In conclusion, the data presented here indicate that the CD4+ T cell intrinsic expression of functional Nod2 is capable of modulating T cell signalling yet Nod2 is dispensable for the T cell induction and regulation of colitis and for both the development and the function of CD4+ Treg cells." (PMID 24324812, 2013). "In addition, the role of T cell intrinsic Nod2 in regulatory T cell (Treg) development and function during colitis remain to be analyzed." (PMID 24324812, 2013). "Although activation of NF-kB plays a pivotal role in the activation, differentiation and proliferation of T cells, we observed that transfer of Nod2 deficient naive CD4+CD45RBhigh T cells in Rag1-/- mice did not impair the induction of colitis." (PMID 24324812, 2013). "Although Nod2 deletion in CD4+ T cells has been shown to impair the induction of colitis in the murine T cell transfer model, the analysis of T cell intrinsic Nod2 function in T cell differentiation and T cell-mediated immunity is inconsistent between several studies." (PMID 24324812, 2013). "Nevertheless, NOD2-deficient mice do not develop spontaneous colitis when kept under specific pathogen free (SPF) conditions." (PMID 24409180, 2013). "In addition, the role of Nod2 in Treg cell function and prevention of T cell-induced colitis remains to be analyzed." (PMID 24324812, 2013). "Finally, we also examined if Card15/Nod2 deficiency affects the colonic response to 2,4,6-trinitrobenzene sulphonic acid (TNBS), a classic experimental model of colitis in mouse." (PMID 17565376, 2007). "Secondly, since GALT is reported to modulate the severity of TNBS-induced colitis it can be hypothesised that the TNBS induced colitis is exacerbated in Card15/Nod2 KO mice because of GALT overdevelopment." (PMID 17565376, 2007). "Collectively, these in vitro and in vivo studies strongly suggest that MDP activation of NOD2 inhibits TLR9-induced type I IFN responses through the removal of the K63-linked polyubiquitination of TRAF3 by OTUD5 activation, and thereby suppresses the development of TLR9-induced colitis." (PMID 41155222, 2025). "Indeed, the blockade of DUBA-mediated deubiquitination of TRAF3 by DUBA-specific siRNA cancelled the negative regulatory effects of NOD2 on DSS-induced colitis in mice treated with CpG, and mice treated with DUBA-siRNA displayed severe DSS-induced colitis even after repeated MDP injections." (PMID 39403381, 2024).
colitis (continued). "The NOD1 expression in T cells could impede the colitis-associated intestinal tumorigenesis through mediating the IFN-γ signaling, and NOD2 could suppress the tumorigenesis of colitis-associated cancer by downregulating NF-κB and MAPK pathways with the induction of IRF4." (PMID 39135979, 2024). "In a TNBS-induced colitis model, treatment with Lactobacillus peptidoglycan increased the number of Tregs in mesenteric lymph nodes and elevated IL-10 expression in the colonic mucosa, implying that NOD2 activity within the intestinal mucosa fosters a milieu conducive to immune tolerance." (PMID 38507159, 2024). "We first assessed whether Nod2 expression in myeloid cells, including monocyte-derived phagocytes such as monocyte-derived dendritic cells (mo-DCs) and macrophages (mo-Macs), may modulate the myeloid content at steady state and upon acute colitis." (PMID 37876927, 2023). "We further confirmed whether NOD2 signaling mediated LPH’s anti-colitis effects." (PMID 37286542, 2023). "Also, after NOD2 was deleted in IL-10−/− mice, the symptoms of colitis were significantly improved." (PMID 37833958, 2023). "However, the role of Nod2 in myeloid cells in a model of acute colitis and colitis-associated colon cancer (CAC) has not been clearly elucidated." (PMID 37876927, 2023). "In these studies, we took advantage of the fact that NOD2 cross-regulation can be assessed by intra-peritoneal administration of exogenous MDP so as to cause enhanced NOD2 stimulation and thus inhibition of experimental colitis, such as DSS-colitis or TNBS-colitis." (PMID 36189261, 2022). "Thus, studies of transgenic mice carrying a transgene with BS-associated NOD2 mutation also support the view that over-expressed BS-NOD2 fails to protect mice from developing colitis upon TNBS challenge." (PMID 36189261, 2022). "Interestingly, PSA in outer membrane vesicle-induced signaling in DCs requires IBD-associated genes, ATG16L1 and NOD2, to activate a non-canonical autophagy pathway during protection from colitis." (PMID 32719681, 2020). "Furthermore, mice deficient of NOD1, NOD2 or double knockout mice for NOD1 and NOD2 are extremely susceptible to chemically-induced colitis due to increased barrier permeability and lack of efficient epithelial tissue repair." (PMID 24886810, 2014). "Alike the SIGNR3−/− mice in our study, mice lacking NOD2 are more susceptible to colitis." (PMID 23882266, 2013). "Indeed, an initial report suggested that T cell intrinsic NOD2 was important for CD4 T cell-dependent IFNγ responses to control Toxiplasma gondii in mice as well as for induction of colitis in an adoptive transfer model in which WT or NOD2−/− CD4 T cells were transferred into RAG−/− mice." (PMID 23405246, 2013). "In DSS-induced colitis mice, treatment with DEH (10, 20 mg/kg) or SASP (50 mg/kg) significantly reduced NOD2 protein levels." (PMID 40468178, 2025). "Each of the 13 bacteria demonstrated positive or negative correlations with at least one AOM/DSS-induced CAC parameter, colitis/CRC indicators, or genes related to the NOD2/NF-κB signaling pathway." (PMID 40734913, 2025). "To address the significance of YOD1 in NOD2 signal transduction in vivo, we studied the effect of MDP treatment on DSS colitis in Yod1+/+ and Yod1−/− mice." (PMID 39333628, 2024). "Since NOD2 signaling is protective in IBD, MDP administration protects mice from DSS-induced colitis and this protective effect of MDP is lost in mice with defective NOD2 signaling." (PMID 39333628, 2024). "NOD2-mediated negative regulation of TLR2-mediated Th1 responses, which was initially reported in in vitro studies, was also observed in an in vivo colitis model." (PMID 39403381, 2024). "The deubiquitinating enzyme YOD1 potentiates protective NOD2 signaling by stabilizing RIPK2, thereby ameliorating intestinal inflammation and colitis." (PMID 39333628, 2024). "We then turned our attention to the role of the crosstalk between NOD2 and TLR9 in experimental colitis." (PMID 39403381, 2024).